RBP4 (retinol binding protein 4)
Diseases named in the same sentence as RBP4 in open-access papers (continued):
Sharing a sentence is not in itself a finding about the gene and the disease.
Insulin resistance (continued). "RBP4 was reported to be a fat-derived adipokine, inducing insulin resistance in the liver and skeletal muscle." (PMID 35739894, 2022). "Several studies have suggested a direct role of RBP4 in promoting AT inflammation and lipolysis, which contributes to obesity-induced insulin resistance and liver steatosis." (PMID 35909571, 2022). "RBP4 is involved in the regulation of insulin and insulin resistance, which would affect fetal growth." (PMID 35505881, 2022). "There was an increase in RBP4, which is expressed during the differentiation of monocytes into primary macrophages and plays an important role in the development of insulin resistance in adipose tissue." (PMID 35625760, 2022). "Kahn and collages described immune cell infiltration as concomitant with cytokine secretion by adipose tissue, leading to insulin resistance by retinol-binding protein 4 (RBP4)." (PMID 35563955, 2022). "Then, a growing body of evidence has supported the involvement of RBP4 on obesity and insulin resistance in humans." (PMID 35369314, 2022). "In fact, RBP4 is an adipokine related to the dysregulation of energy metabolism, insulin resistance, diabetes mellitus and obesity, and it was reported to play a role also as an inflammatory neurotrophic adipokine." (PMID 35215406, 2022). "A correlation analysis between the changes in serum RBP-4 levels and glycaemic control and insulin resistance parameters, including HOMA-IR, HOMA-β, and HOMA-IS scores and FBG, Fins, and 2 h-BG levels, was performed for all participants." (PMID 35547000, 2022). "Transgenic overexpression of RBP4 orchronic RBP4 administration induces whole-body insulin resistance and RBP4deletion improves insulin action in mice." (PMID 39076230, 2022). "Another study positively correlated serum RBP4 levels with insulin resistance and additionally showed that improving insulin sensitivity through exercise lowers RBP4 levels." (PMID 35334893, 2022). "Aberrant mitochondrial oxidative phosphorylation occurs in obese females with type 2 diabetes and insulin resistance, which are related to RBP4." (PMID 34068244, 2021). "Taken together, our data provides possible clues for the potential of RBP4 as targets of insulin resistance in HUA patients." (PMID 34177800, 2021). "The decrease in RBP4 secretion represents the decline in pancreatic function and aggravates insulin resistance." (PMID 34122100, 2021). "This study proves a definitive relationship between retinol-binding protein-4 and insulin resistance and coronary artery disease severity." (PMID 34571734, 2021). "Many studies, including ours, have shown that RBP4 is an adipocyte protein that is crucially involved in regulating insulin resistance, metabolic syndrome, the inflammation process, and human cancer tumorigenesis." (PMID 33834191, 2021). "In insulin-resistant mice, RBP4 expression is high in AT, and AT RBP4 mRNA expression is correlated with serum RBP4 levels." (PMID 33671547, 2021). "In humans, RBP4 levels in serum have been found to be related to many metabolic diseases, such as insulin resistance, type 2 diabetes mellitus, and obesity." (PMID 34068244, 2021). "Although the role of RBP4 in glucose metabolism has been extensively studied, the regulatory networks of RBP4 in obesity, insulin resistance and diabetes are still poorly understood." (PMID 34373742, 2021). "RBP4 is a newly identified circulating adipokine involved in insulin resistance, which is the vital extracellular transporter responsible for binding and transporting retinol in the blood." (PMID 34956579, 2021). "So far, RBP4 has been presented as a deleterious adipokine which promotes insulin resistance, obesity and cardiovascular diseases." (PMID 34638803, 2021). "In studies of insulin responsiveness, RBP4 has attracted much research interest in the last decade owing to its effects on insulin resistance." (PMID 33679618, 2021).
Insulin resistance (continued). "For example, a protein complex, which includes transthyretin (TTR), serum retinol-binding protein (RBP4), and retinol (ROH), was presented in peripheral blood and known to be associated with the development of insulin resistance." (PMID 32724825, 2020). "In particular, the adipokines resistin, leptin, PAI-1, and retinol binding protein 4 (RBP4) induce insulin resistance in megakaryocytes by interfering with IRS-1 expression with a negative impact on insulin signaling in platelets." (PMID 31963572, 2020). "Retinol-binding protein 4 plays a role in progression of insulin resistance through inflammatory markers." (PMID 32864980, 2020). "By contrast, a randomized and double-blind trial revealed that after 16 weeks of sitagliptin administration, serum levels of RBP4 were significantly decreased in the treatment group, which was positively correlated with improved insulin resistance parameters." (PMID 31921323, 2020). "RBP4 is produced by visceral adipocytes and other tissues, and can activate and promote adipose tissue inflammation, which contributes to insulin resistance." (PMID 33383883, 2020). "In fact, its deficiency normalized the glucose transporter-4 (GLUT4) expression in cardiomyocytes and attenuated hypertrophic response to pressure overload, whereas TLR4 or MyD88 knockdown attenuated RBP4-induced insulin resistance and cardiac hypertrophy." (PMID 33324685, 2020). "Multivariable linear regression analysis was conducted to assess the influence of RBP4 levels on insulin resistance." (PMID 31921323, 2020). "Several clinical studies have shown positive correlation between adipokine RBP-4 levels and insulin resistance, BMI, and dyslipidemia." (PMID 33133591, 2020). "RBP-4 has been suggested to be a novel adipokine linking obesity with systemic insulin resistance and potentially with adiposity-related disorders." (PMID 33133591, 2020). "Retinol-binding protein-4 (RBP-4) is a novel adipokine or hepatocytic cytokine, and its high serum levels have been associated with insulin resistance and obesity." (PMID 32449048, 2020). "Mechanism studies found that RBP4 was involved in the pathogenesis of diabetes by inducing insulin resistance through several etiologic pathways." (PMID 31921323, 2020). "Adipose-specific GLUT4 knockout [adipose-Glut4 (−/−)] mice show insulin resistance is related to increased RBP4 expression." (PMID 31956345, 2020). "RBP4 is involved in the insulin resistance process, where the upregulation of RBP4 was highly associated with obesity and diabetes type 2 problems." (PMID 33029159, 2020). "More recently, RBP4 has been described as an adipokine that is involved in insulin resistance and metabolic syndrome (MetS)." (PMID 32095874, 2020). "RBP4 has recently been described as an adipokine that contributes to insulin resistance and diabetes, partly via activation of antigen-presenting cells." (PMID 31936359, 2020). "The blood serum levels of RBP4 correlates significantly with other major factors related to insulin resistance such as triglyceride, cholesterol and blood pressure." (PMID 31953481, 2020). "RBP4 has been shown to correlate with insulin resistance, and its circulating level elevates in diabetes, obesity, and metabolic disorders." (PMID 31278889, 2019). "Retinol-binding protein 4 (RBP-4) is an adipokine involved in the pathogenesis of insulin resistance." (PMID 31824900, 2019). "Studies have shown that circulating RBP4 levels correlate with the magnitude of insulin resistance in obese subjects and in those with impaired glucose tolerance and type 2 diabetes mellitus." (PMID 31051472, 2019). "Retinol-binding protein 4 (RBP4) is a plasma retinoid transporter detected in the early phase of insulin resistance conditions, such as in T2DM and MS; its inhibition allowed an increase in insulin sensitivity in animal trials." (PMID 31658729, 2019).
Insulin resistance (continued). "Considering the sensitivity of RBP4 to show the insulin resistance, our study points out that long-term treatment with isotretinoin increases the insulin resistance in patients with AV." (PMID 30761880, 2019). "Retinol-binding Protein 4 mediates retinol transport in blood plasma and is involved in regulating insulin resistance." (PMID 30951540, 2019). "In addition to inducing insulin resistance, RBP4 may also have impact on insulin secretion from beta-cells, as genetic studies have shown that SNP risk alleles rs3758539 (A) and rs34571439 (G) in the RBP4 gene were associated with reduced insulin secretion." (PMID 30651745, 2019). "In humans, increased circulating RBP4 levels have been correlated with obesity, insulin resistance, and type-2 diabetes." (PMID 30782214, 2019). "Serum RBP4 levels are highly expressed under insulin resistance conditions related to obesity and T2DM." (PMID 31208019, 2019). "In rodent studies, Rbp4 overexpression was convincingly shown to enhance insulin resistance, impair insulin signaling in muscle and induce pathways involved in hepatic gluconeogenesis." (PMID 31717719, 2019). "Retinol-binding protein 4 (RBP4), a cytokine secreted by adipocytes, led to insulin resistance and negatively correlated with the expression of GLUT-4 in insulin-resistant states." (PMID 31396083, 2019). "In human studies, decreasing blood RBP4 levels by drug therapies improved insulin resistance, and a link between RBP4 gene and type 2 diabetes has been found in genetic studies." (PMID 30651745, 2019). "Since adipose tissue is considered a contributor to elevated serum RBP4 levels in the state of insulin resistance, we tested the glucose tolerance of the bulls." (PMID 31147589, 2019). "RBP4 has been well known as an important adipokine that contributes to insulin resistance both in rodent and human." (PMID 31278889, 2019). "In our cohort, we found that MR-proANP is strongly correlated with adipocytokines such as adiponectin, RBP4 and resistin, which are important mediators of insulin resistance and metabolic alterations." (PMID 31830996, 2019). "Adipose RBP4 mRNA levels, especially in the visceral fat, are inversely correlated with GLUT4 mRNA and are positively linked with adiposity in insulin resistance." (PMID 31208019, 2019). "High expression of Retinol Binding Protein 4 (RBP4) is responsible for the development of insulin resistance in obesity and NIDDM." (PMID 30678306, 2019). "Although we did not observe a concomitant reduction in PPAR and CD36 in adipose tissue, we did observe reduction of the insulin resistance markers RBP4 and resistin in this organ." (PMID 29691457, 2018). "The immune-related protein RBP4 is an adipokine that contributes to insulin resistance; RBP4 likely modulates pathophysiological processes during bacterial infection." (PMID 29636444, 2018). "Plasma glucose and RBP4 concentration (an adipokine related to insulin resistance) remained stable during pregnancy, and insulin concentration and HOMA index only increased at 32 weeks of pregnancy." (PMID 30127377, 2018). "Second, a previous study suggested that baseline RBP4 predicted insulin resistance (OR = 1.44, P=0.015) in the 10-year follow-up phase in Beijing Child and Adolescent Metabolic Syndrome study." (PMID 30135138, 2018). "Nevertheless, the results of the present study suggest associations between RBP4, TTR, TG, and insulin resistance." (PMID 29747616, 2018). "Plasma retinol-binding protein (RBP4) and its overexpression is a biomarker for insulin resistance, prediabetes and T2DM, the metabolic syndrome, and myocardial infarction." (PMID 30211220, 2018). "An association between increased levels of both RBP4 and TTR and an elevated risk of insulin resistance (the precursor state to T2DM) and CVD (the macrovascular complication of diabetes) has been reported in several studies." (PMID 29747616, 2018).
Insulin resistance (continued). "Insulin resistance was correlated with fasting levels of insulin and leptin/adiponectin (r = 0.913); of insulin, retinol binding protein 4 and leptin/adiponectin (r = 0.903); and of insulin, glycated albumin, and leptin/adiponectin (r = 0.913)." (PMID 29610560, 2018). "Multiple studies have found that the level of RBP4 was elevated in obesity, T2DM, and other insulin-resistant diseases, which has explained the underlying association of RBP4 and insulin resistance (IR) as well as diabetes." (PMID 30186876, 2018). "Overexpression of Rbp4 in adipocytes is reported in the conditions of insulin resistance, metabolic syndrome, and obesity." (PMID 30211220, 2018). "While it has been shown that elevated serum RBP4 levels manifest in the development of systemic insulin resistance in rats, evidence for an effect of RBP4 on obesity and insulin resistance in humans is controversial." (PMID 29747616, 2018). "Probably, in our case elevated plasma levels of RBP4, as well as sCD36 (a trend) are indicators of obesity along with developing insulin resistance state and cardiovascular disorders." (PMID 29335416, 2018). "Serum RBP4 concentration correlated positively with the magnitude of insulin resistance in subjects with obesity or diabetes." (PMID 30374329, 2018). "Our findings provided clues for the prevention of insulin resistance and inflammation-related chronic diseases via the use of carotenoid rich-foods in the diet aimed at lowering serum RBP4 levels." (PMID 29495330, 2018). "RBP4 is another adipocyte-derived factor, reported to be involved in the onset of adiposity and insulin resistance." (PMID 29740397, 2018). "The improvement in glucose tolerance and insulin sensitivity in TG9 mice correlated with a ~60% decrease in insulin resistance markers retinol-binding protein 4 (RBP4) and resistin in epidydimal fat pads isolated from ritonavir-treated animals." (PMID 29691457, 2018). "We therefore tested the effect of hyperinsulinemia, hyperandrogenism, or the combination of hyperandrogenism and insulin resistance on RBP4 expression." (PMID 29719598, 2018). "There are contradictory data concerning close connection between raised values of circulating RBP4 and development of insulin resistance." (PMID 29335416, 2018). "In spontaneously hypertensive rats with insulin resistance, treadmill running reduced circulating RBP4 concentrations." (PMID 30374329, 2018). "The present study aims to investigate the levels of leptin, resistin, visfatin, SFRP5, MCP-1/CCL2, and RBP4 as well as their correlations with insulin resistance and clinical parameters of overweight and T2DM in a Vietnamese study group." (PMID 29785210, 2018). "It has recently been suggested that inflammation produced by RBP4 induces insulin resistance and CVD." (PMID 30038059, 2018). "Retinol binding protein 4 (RBP4), a protein secreted by adipocytes and bound in plasma to transthyretin (TTR), has been associated with obesity, the early phase of insulin resistance, metabolic syndrome, and type 2 diabetes mellitus." (PMID 29747616, 2018). "Circulating levels of RBP4 were found to correlate with insulin resistance, impaired glucose tolerance and type 2 diabetes, and metabolic syndrome; subsequent studies also suggested that the associations of RBP4 with cardiovascular disease (CVD,)." (PMID 30038059, 2018). "It was reported that the level of circulating RBP4 is often elevated in obese mice and humans and that, under these circumstances, the protein induces insulin resistance." (PMID 30135138, 2018). "As markers of glucose homeostasis within adipose tissue, RBP4, GLUT4, and IDE are all associated with the presence of insulin resistance." (PMID 28303117, 2017). "The data concerning serum retinol-binding protein 4 (RBP4), an adipocytokine involved in systemic insulin resistance, are inconclusive." (PMID 27473078, 2017).
Insulin resistance (continued). "For instance, a recent study conducted on obese mice showed that lowering RBP4 level by disrupting TTR was effective in improving insulin resistance and adipose tissue inflammation." (PMID 28713486, 2017). "It is also possible that there is a relationship between insulin resistance and specific RBP-4 isoforms (isoform 2 specifically)." (PMID 28670222, 2017). "Transgenic overexpression of human RBP4 in mice or injection with recombinant RBP4 in normal mice led to insulin resistance." (PMID 29286303, 2017). "In humans, a number of studies have shown that increased circulating RBP4 levels were correlated with obesity, insulin resistance, impaired glucose tolerance and type 2 diabetes mellitus (T2DM)." (PMID 28931435, 2017). "Retinol binding protein 4 (RBP4) is implicated in obesity, insulin resistance and type 2 diabetes mellitus that are closely associated with nonalcoholic fatty liver disease (NAFLD)." (PMID 28931435, 2017). "Retinol Binding Protein 4 (RBP4) is mainly excreted by the kidney and plays a pivotal role in insulin resistance (IR)." (PMID 29333450, 2017). "As a cell surface receptor of RBP4, STRA6 activated JAK2-STAT5 signal pathway, induced production of SOCS-3 by combining with retinol-RBP4 complexes, and led to insulin resistance to promote the occurrence of T2DM." (PMID 27446956, 2016). "After sacrifice, biochemical markers of obesity and insulin resistance including oral glucose tolerance test, adiponectin, leptin, and retinol binding protein-4 (RBP4) were measured." (PMID 26842399, 2016). "Retinol binding protein 4 (RBP4), which is a principle carrier of blood retinol, contributes insulin resistance in mice and humans." (PMID 26901059, 2016). "Accordingly, leptin, retinol binding protein 4 (RBP4), adiponectin and several other adipocytokines are reported to play a role in the regulation of insulin resistance and lipid metabolism." (PMID 26924713, 2016). "In this regard, RBP4 has been correlated not only with obesity and insulin resistance but also with inflammatory factors such as C-reactive protein and IL-6." (PMID 27376090, 2016). "Total IR was upregulated in PLB4 vs WT mice, together with RBP4, thus corroborating links with insulin resistance." (PMID 27138913, 2016). "In nonobese subjects, decreased expression of glucose transporter type 4 (GLUT-4) in adipocytes predicts increased serum RBP4 levels and insulin resistance." (PMID 26975349, 2016). "As the levels of RBP4 are inversely correlated with the expression of GLUT4 in adipocytes, it has been postulated that elevated RBP4 contributes to insulin resistance downregulating GLUT4." (PMID 27376090, 2016). "Previous studies show that RBP4 levels are correlated with indices of insulin resistance, which would be interesting to assess in future studies." (PMID 25119682, 2015). "RBP4 as an adipokine has been shown to induce insulin resistance and GLUT4 to mediate insulin-stimulated glucose uptake in EF." (PMID 25935836, 2015). "Emerging evidence suggests possible roles for proinflammatory pathways in RBP4-induced insulin resistance." (PMID 25918733, 2015). "Clinical studies in children and adolescents have demonstrated that RBP4 has a role in obesity and the development of insulin resistance and type 2 diabetes." (PMID 26132231, 2015). "It has also been recently reported that RBP4 is involved in the early phases of developing adiposity and insulin resistance." (PMID 26132231, 2015). "Elevated serum RBP4 induces insulin resistance in the liver by increasing the expression of phosphoenolpyruvate decarboxylase (PEPCK) and hepatic glucose output." (PMID 25918733, 2015). "Retinol-binding protein-4 (RBP-4) is mainly produced by visceral adipose tissue and plays a major role in insulin resistance." (PMID 25161652, 2014). "In this study, adipocyte-specific deletion of GLUT4 led to increased RBP4 expression and the development of insulin resistance." (PMID 25479076, 2014).